TIPIN (TIMELESS interacting protein)
Description:
Plays an important role in the control of DNA replication and the maintenance of replication fork stability. Important for cell survival after DNA damage or replication stress. May be specifically required for the ATR-CHEK1 pathway in the replication checkpoint induced by hydroxyurea or ultraviolet light. Forms a complex with TIMELESS and this complex regulates DNA replication processes under both normal and stress conditions, stabilizes replication forks and influences both CHEK1 phosphorylation and the intra-S phase checkpoint in response to genotoxic stress.
Synonyms: FLJ20516
Tractability: Small molecule: a structure with a bound ligand is known. PROTAC: ubiquitination databases record sites on it.
Gene: Protein-coding gene on chromosome 15 (66,336,191 to 66,386,746, reverse strand). Ensembl gene ENSG00000075131.
Subcellular location: Cytoplasm; Nucleus
Pathways (Reactome):
DNA Repair: Processing of DNA double-strand break ends
Gene Ontology:
Molecular function: protein binding; DNA binding
Biological process: cell cycle phase transition; DNA replication checkpoint signaling; mitotic intra-S DNA damage checkpoint signaling; positive regulation of cell population proliferation; regulation of nuclear cell cycle DNA replication; replication fork arrest; replication fork processing; DNA damage response
Cellular component: chromatin; cytoplasm; nucleus; replication fork protection complex; nuclear replication fork; nucleoplasm
Genetic constraint (gnomAD): Loss-of-function variants: 24 observed, 31.37 expected, observed/expected ratio (o/e) 0.77, 90% interval 0.55 to 1.08. The upper end of that interval is the gene's LOEUF score, 1.08, which puts it in group 4 of 6, group 1 being the genes least tolerant of losing a copy. Missense variants: 280 observed, 333.11 expected, observed/expected ratio (o/e) 0.84, 90% interval 0.76 to 0.93. Synonymous variants: 90 observed, 116.8 expected, observed/expected ratio (o/e) 0.77, 90% interval 0.65 to 0.92.
Homologues: Orthologues: chimpanzee TIPIN (99% identical), macaque TIPIN (94% identical), pig TIPIN (81% identical), dog TIPIN (78% identical), rabbit TIPIN (71% identical), mouse Tipin (70% identical), rat Tipin (68% identical), guinea pig TIPIN (63% identical), zebrafish tipin (44% identical), tropical clawed frog tipin (43% identical), Drosophila melanogaster CG10336 (23% identical), Caenorhabditis elegans tipn-1 (17% identical).
Diseases named in the same sentence as TIPIN in open-access papers:
TIPIN is named in the same sentence as 22 diseases in open-access papers, as found by Europe PMC text mining. Sharing a sentence is not in itself a finding about the gene and the disease. The quoted sentences say what the papers report.
breast carcinoma (4 papers, 2020 to 2022). "Silencing of the TIPIN expression induced apoptosis and inhibited proliferation in breast cancer cell lines, making TIPIN a potential target for breast cancer therapy." (PMID 35082931, 2022). "It was previously reported that the TIPIN mRNA level is significantly upregulated in breast cancer, particularly in the most proliferative and poor prognosis-related breast cancer subtypes (triple negative breast cancer, HER2, and Luminal B)." (PMID 35082931, 2022). "In the studies related to DNA damage, TIPIN is considered to be important in the cell cycle arrest and maintenance of DNA replication, and the depletion of TIPIN can lead to apoptosis in breast cancer cells." (PMID 35158649, 2022). "Previous studies have found that the expression of TIPIN was higher in the most aggressive and proliferative breast cancer subtypes compared to healthy breast tissue." (PMID 33816217, 2021). "In the case of TIPIN in breast cancer, TIPIN knockdown in triple negative breast cancer cells decreased tumorigenicity in vitro and delayed tumor growth in vivo." (PMID 32499870, 2020).
melanoma (2 papers, 2020 to 2024). A malignant, usually aggressive tumor composed of atypical, neoplastic melanocytes. "Our survival analysis revealed that high TIM/TIPIN expression is an independent biomarker associated with poorer clinical outcomes in melanoma patients." (PMID 32499870, 2020). "We also discovered that the overexpression of TIM and TIPIN was significantly associated with poorer prognosis of melanoma patients." (PMID 32499870, 2020). "Moreover, we found that TIM and TIPIN expression is highly associated with melanoma." (PMID 32499870, 2020). "To determine the effect of TIM and TIPIN on the tumorigenic capacity of melanoma cells, we investigated the effects of TIM and TIPIN loss on tumor growth in vivo by using shTIM- and shTIPIN-transfected A375 cells." (PMID 32499870, 2020). "Consistent with the findings from other studies, we also found that knock down of TIM and TIPIN compromised proliferation of melanoma cells." (PMID 32499870, 2020). "GEPIA generated box plots with jitter showing differences between TIM and TIPIN expression in melanoma (TCGA tumors vs. TCGA normal)." (PMID 32499870, 2020). "Western blot and real-time-PCR analysis showed that TIM and TIPIN were significantly elevated in melanoma cells compared with normal melanocytes." (PMID 32499870, 2020). "The results show that TIM and TIPIN were significantly upregulated in melanoma tissue compared to normal tissue." (PMID 32499870, 2020). "Our study demonstrated that the TIM/TIPIN complex is abundantly expressed in melanoma compared with normal melanocytes." (PMID 32499870, 2020). "Because the TIM/TIPIN complex is involved in DNA replication fork stability, we investigated the mechanisms behind the melanoma cells to undergo apoptosis following TIM or TIPIN deletion." (PMID 32499870, 2020). "Lentivirus-mediated TIM/TIPIN knockdown in A375 melanoma cells was used to examine proliferation, colony formation, and apoptosis." (PMID 32499870, 2020). "TIM and TIPIN depletion diminished the tumorigenicity of melanoma xenografts in immunocompromised mice." (PMID 32499870, 2020). "Altogether, our data suggest that TIM and TIPIN knockdown leads to apoptosis in melanoma cells." (PMID 32499870, 2020). "Our results suggest that the TIM/TIPIN complex plays an important role in tumorigenesis of melanoma, which might reveal novel approaches for the development of new melanoma therapies." (PMID 32499870, 2020). "In this study, we characterized the role of TIM and TIPIN in melanoma." (PMID 32499870, 2020). "The TIM/TIPIN complex is frequently overexpressed in melanoma cells compared to normal melanocytes." (PMID 32499870, 2020). "High expression of TIM is associated with poor prognosis in melanoma patients, whereas TIPIN expression does not affect overall survival of patients." (PMID 32499870, 2020). "We conducted a series of studies to examine the role of the TIM/TIPIN complex in melanoma." (PMID 32499870, 2020). "Overall, these results suggest that TIM and TIPIN are upregulated in melanoma." (PMID 32499870, 2020). "In summary, our study demonstrates that TIM and TIPIN each are overexpressed in melanoma cells, and could regulate proliferation and migration of melanoma cells." (PMID 32499870, 2020). "Overall, these results suggest that TIM and TIPIN promote tumorigenicity of melanoma cells in vivo." (PMID 32499870, 2020). "TIM and TIPIN form a stable complex and serve as a key player in controlling melanoma." (PMID 32499870, 2020). "Thus, TIM and TIPIN might be a potential marker for melanoma and a good prognostic marker for melanoma patients, although further studies are required." (PMID 32499870, 2020). "Thus, the TIM/TIPIN complex might be an effective biomarker for melanoma and for determining optimal treatments in melanoma patients." (PMID 32499870, 2020). "Targeting TIM/TIPIN might be a potential therapeutic strategy against melanoma." (PMID 32499870, 2020).
melanoma (continued). "Overall, the work presented herein provides new avenues for the development of more potent antibodies and small-molecule inhibitors of the TIM/TIPIN complex that could be used alone or in combination with small-molecule inhibitors, which could be a promising drug to treat melanoma in the future." (PMID 32499870, 2020). "The more interesting ones, confirmed by the bibliography on melanoma, are as follows: USP15, TIPIN, TMC5, TYMP, USP19, USP8, and TFAP2B." (PMID 38928466, 2024). "To investigate the role of TIM and TIPIN in the progression of melanoma, we first analyzed TIM and TIPIN expression in 461 melanoma tissue samples and 558 normal tissue samples from The Cancer Genome Atlas (TCGA) Data Portal." (PMID 32499870, 2020). "Our series of in vitro and in vivo tumorigenesis studies revealed that the proliferation potential of melanoma cells was significantly inhibited after knockdown of TIM and TIPIN." (PMID 32499870, 2020). "To assess the role of the TIM/TIPIN complex in melanoma, we analyzed TIM/TIPIN expression data from the publicly accessible TCGA online database, Western blot analysis, and RT-qPCR in a panel of melanoma cell lines." (PMID 32499870, 2020). "The current study demonstrates that TIM and TIPIN are overexpressed in melanoma and examines the effects of short hairpin RNA (shRNA)-mediated TIM knockdown on growth, apoptosis, and tumor formation by using the A375 melanoma cell line." (PMID 32499870, 2020).
cervical cancer (1 paper, 2021). A primary or metastatic malignant neoplasm involving the cervix. "Tissue samples from cervical cancer were picked out in the Human Protein Atlas and the expression levels of TIPIN and POLA1 were confirmed by immunohistochemistry." (PMID 33816217, 2021). "Our research provides a co-expression network of gene modules and identifies TIPIN and POLA1 as stable potential prognostic biomarkers for cervical cancer." (PMID 33816217, 2021). "Hierarchical clustering and Gepia results indicated that the expression quantity of hub genes NDC80, TIPIN, MCM3, MCM6, POLA1, and PRC1 may determine the prognosis of cervical cancer." (PMID 33816217, 2021).
depression (1 paper, 2010). "NPAS2 rs12712083, as well as a non-synonymous coding SNP located on exon 5 rs2063690 of TIPIN (Ala111Gly), were associated with depression and fatigue (P = 0.045, OR = 0.72 and P = 0.037, OR = 1.71, respectively)." (PMID 20174623, 2010).
kidney cancer (1 paper, 2016). Primary or metastatic malignant neoplasm involving the kidney. "Downregulation of TIM and TIPIN was found in kidney cancer patients compared to normal kidney tissue." (PMID 27492458, 2016).
liver cancer (1 paper, 2022). An epithelial or non-epithelial malignant neoplasm that arises from the liver. "Overall, our results showed that the four specific genes, TIPIN, RBM15B, DUSP28, and TRIM31, were likely prognostic biomarkers of liver cancer, and TIPIN might conspicuously accelerate the process of hepatocarcinogenesis." (PMID 35082931, 2022).
liver disease (1 paper, 2022). "This suggests that TIPIN may promote the progression of liver disease." (PMID 35082931, 2022).
malaria (1 paper, 2014). Malaria is a serious and sometimes fatal disease caused by a parasite that commonly infects a certain type of mosquito which feeds on humans. "In the severe malaria groups, intracellular proteins (TIPIN, MSRB1), components of glucose metabolism (ADSSL1, DNPEP1) and an inflammatory protein (DAPK1) had increased levels, further confirming observations made above with the ‘targeted array’." (PMID 24743550, 2014).
metastatic carcinoma (1 paper, 2021). A carcinoma which has spread from the original site of growth to another anatomic site. "The results showed that gene expression in metastatic carcinoma was lower than that in cancer primary cells, which indicated that lower gene expression of TIPIN and POLA1 was correlated with poor clinical outcomes." (PMID 33816217, 2021).
myotonic dystrophy type 1 (1 paper, 2023). Steinert disease, also known as myotonic dystrophy type 1, is a muscle disease characterized by myotonia and by multiorgan damage that combines various degrees of muscle weakness, arrhythmia and/or cardiac conduction disorders, cataract, endocrine damage, sleep disorders and baldness. "In human cells, depletion of TIM, TIPIN, or CLASPIN greatly accelerates CTG(n)·CAG(n) repeat expansion, thus resulting in the chromosomal instability associated with myotonic dystrophy type 1 (DM1)." (PMID 36892674, 2023).
cancer (5 papers, 2020 to 2022). A tumor composed of atypical neoplastic, often pleomorphic cells that invade other tissues. "Firstly, TIMELESS and TIPIN are co‐ordinately over‐expressed in many human cancer cells, where they are important to combat the inherent DNA replication stress that is a feature of the cancerous state." (PMID 34269473, 2021). "Our findings supported other work where scientists reported the importance of TIM/TIPIN in many different types of human cancers." (PMID 32499870, 2020). "In contrast, only a very limited number of studies have been conducted to determine the role of TIPIN in cancer." (PMID 32499870, 2020). "This study reveals that TIM is upregulated in cancer tissues compared to normal urothelial biopsies and TIPIN mRNA levels exhibited a similar trend although the increased protein expression in cancer tissue was more modest." (PMID 32499870, 2020). "RBM15B and TIPIN showed significant differences in the stages of cancer development." (PMID 35082931, 2022). "The results showed that the TIPIN level was altered between cancer and paracancerous tissues." (PMID 35082931, 2022). "The information regarding the role of the TIM/TIPIN complex in cancer is very limited." (PMID 32499870, 2020). "According to a series of analysis, TIPIN and POLA1 were recognized to both participate in cancer progression of CC." (PMID 33816217, 2021). "Among them, the expression of TIPIN, TIMELESS, ARNTL2, ARNTL, and AANAT are positively correlated with the infiltration level of tumor‐infiltrating lymphocytes in pan‐cancer, respectively." (PMID 31927791, 2020).
tumor (4 papers, 2016 to 2022). "Among which, SLC25A15, RAD9A, PRF19, THOC1, and TIPIN were significantly overexpressed in tumor tissues in both the TCGA and our local cohorts." (PMID 36033441, 2022). "Immunohistochemistry was performed on tumor tissues, and interestingly, the results showed that the expression level of PCNA in the TIM- and TIPIN-knock down groups was significantly reduced, suggesting a marked inhibition of cell proliferation." (PMID 32499870, 2020). "In a xenograft tumor nude mouse model, shRNA-knockdown of TIM/TIPIN significantly reduced tumor growth." (PMID 32499870, 2020).
infection (1 paper, 2020). The state of being infected such as from the introduction of a foreign agent such as serum, vaccine, antigenic substance or organism. "The TIPIN gene product is the TIMELESS-interacting protein, which has been implicated in Epstein–Barr viral replication and at the pathway level during infection with zika, a related flavivirus." (PMID 33302579, 2020).
TIPIN also shares sentences with these, for which no sentence is quoted: triple-negative breast carcinoma (2 papers); colon cancer (1); colorectal cancer (1); Fanconi anemia (1); hepatocellular carcinoma (1); mucopolysaccharidosis type 2 (1); ovarian carcinoma (1); rectal cancer (1); Telangiectasia (1).